MRPL21 (mitochondrial ribosomal protein L21)
Synonyms: L21mt; MRP-L21; bL21m
Tractability: Small molecule: a structure with a bound ligand is known. PROTAC: ubiquitination databases record sites on it; its protein half-life has been measured.
Target class: Other cytosolic protein
Gene: Protein-coding gene on chromosome 11 (68,891,276 to 68,903,835, reverse strand). Ensembl gene ENSG00000197345.
Subcellular location: Mitochondrion
Subcellular location (Human Protein Atlas): Mitochondria; Nucleoplasm
Pathways (Reactome):
Metabolism of proteins: Mitochondrial ribosome-associated quality control; Mitochondrial translation elongation; Mitochondrial translation initiation; Mitochondrial translation termination
Gene Ontology:
Molecular function: RNA binding; structural constituent of ribosome
Biological process: mitochondrial translation; translation
Cellular component: mitochondrial large ribosomal subunit; mitochondrion; mitochondrial inner membrane; cytoplasm; ribosome
Genetic constraint (gnomAD): Loss-of-function variants: 19 observed, 28.91 expected, observed/expected ratio (o/e) 0.66, 90% interval 0.46 to 0.96. The upper end of that interval is the gene's LOEUF score, 0.96, which puts it in group 4 of 6, group 1 being the genes least tolerant of losing a copy. Missense variants: 249 observed, 261.25 expected, observed/expected ratio (o/e) 0.95, 90% interval 0.86 to 1.06. Synonymous variants: 98 observed, 106.15 expected, observed/expected ratio (o/e) 0.92, 90% interval 0.78 to 1.09.
Homologues: Orthologues: chimpanzee MRPL21 (99% identical), macaque MRPL21 (93% identical), mouse Mrpl21 (81% identical), guinea pig MRPL21 (80% identical), rat Mrpl21 (76% identical), zebrafish mrpl21 (56% identical), tropical clawed frog mrpl21 (45% identical), Caenorhabditis elegans mrpl-21 (29% identical), Drosophila melanogaster mRpL21 (29% identical).
Diseases named in the same sentence as MRPL21 in open-access papers:
MRPL21 is named in the same sentence as 20 diseases in open-access papers, as found by Europe PMC text mining. Sharing a sentence is not in itself a finding about the gene and the disease. The quoted sentences say what the papers report.
hepatoma (2 papers, 2020 to 2024).
acute myeloid leukemia (1 paper, 2025). Acute myeloid leukemia (AML) is a group of neoplasms arising from precursor cells committed to the myeloid cell-line differentiation. "The aberrant expression of MRPL21 is associated with a poor prognosis of HCC and with the drug resistance of acute myeloid leukemia (AML) and LUSC." (PMID 39859078, 2025).
colorectal tumors (1 paper, 2021). "bL21m (MRPL21) and uL16m (MRPL16) have been identified as a potential prognostic marker in colorectal tumors." (PMID 34071057, 2021).
head and neck cancer (1 paper, 2025). A primary or metastatic malignant neoplasm affecting the head and neck. "Our study demonstrates that PLL-modified nHAp can effectively deliver MRPL21 siRNA to inhibit tumor growth in vivo, underscoring MRPL21 as a promising therapeutic target and chemosensitizer for head and neck cancer." (PMID 40713706, 2025).
Hyperglycemia (1 paper, 2025). An increased concentration of glucose in the blood. "The identified signature genes (RPS13, MRPS5, MRPL21, MRPL22, NDUFS3) not only unravel the molecular cascade linking maternal hyperglycemia to fetal vascular dysfunction but also offer tangible targets for diagnostic and therapeutic innovation." (PMID 40727584, 2025).
lung adenocarcinoma (1 paper, 2021). A carcinoma that arises from the lung and is characterized by the presence of malignant glandular epithelial cells. "The Cytoscape with cytoHubba tool kits, GEPIA, and c-BioPortal analysis suggested that upregulated hub genes of MRPL22, MRPL28, MRPL21, MRPL12, MRPS12, and MRPL17 are correlated with poor overall survival and may play a key role by cooperating with ALDOA in lung adenocarcinoma." (PMID 34925439, 2021). "Upregulation of MRPL22 (HR = 1.5, p = 0.0048), MRPL28 (HR = 1.5, p = 0.0098), MRPL21 (HR = 1.7, p = 0.001), MRPL12 (HR = 1.7, p = 0.00059), MRPS12 (HR = 1.6, p = 0.002), and MRPL17 (HR = 1.5, p = 0.0051) were correlated with poor overall survival in lung adenocarcinoma." (PMID 34925439, 2021).
lung squamous cell carcinoma (1 paper, 2023). "Moreover, NEDD9, MRPL21, SNRPF, and SCLT1 genes were identified to be involved in lung squamous cell carcinoma drug sensitivity/resistance." (PMID 37185598, 2023).
squamous cell carcinoma (1 paper, 2019). A carcinoma arising from squamous epithelial cells. "Moreover, in samples from clinical squamous cell cancer, six genes (GAL, GSTP1, MRPL11, MRPL21, SF3B2, and YIF1A) at 11q13.1–13.3 and one gene (GALR1) at 18q23 showed significant differences in expression between normal and tumor samples." (PMID 31552180, 2019).
tumor (4 papers, 2019 to 2025). "To investigate the in vivo regulatory role of MRPL21 in tumor progression, we established an HNSCC xenograft model by subcutaneously injecting cells harboring knockdown of MRPL21 and PARP1-overexpressing cells, as well as control cells, into nude mice." (PMID 40713706, 2025). "IHC analysis of tumor tissues further revealed significant downregulation of MRPL21, Ki67, and PARP1 in the drug-treated group." (PMID 40713706, 2025). "MRPL21 promotes tumor proliferation and metastasis by regulating PARP1 expression, and knockdown of PARP1 reverses the oncogenic effects of MRPL21." (PMID 40713706, 2025). "This resistance was significantly attenuated by MRPL21 knockdown, leading to a significant reduction in tumor growth rate, volume, and weight." (PMID 40713706, 2025). "The results demonstrated that PARP1 expression increased upon MRPL21 overexpression and decreased upon MRPL21 knockdown, suggesting that MRPL21 regulates tumor progression by binding to PARP1 and modulating its expression." (PMID 40713706, 2025). "Our results demonstrated that overexpression of MRPL21 downregulated epithelial markers while upregulating mesenchymal markers in tumor cells, suggesting that MRPL21 promotes EMT in these cells." (PMID 40713706, 2025). "Through single-cell sequencing, we identified a subpopulation of cancer cells in HNSCC tumor tissues and metastatic lymph node tissues that express the potential oncogene MRPL21." (PMID 40713706, 2025). "To address this gap, we aimed to develop a drug-delivery system capable of delivering MRPL21 siRNA into tumor cells, thereby effectively targeting the MRPL21 pathway and inhibiting tumor growth." (PMID 40713706, 2025). "We analyzed both highly expressed genes in this subpopulation and in tumor and metastatic tissues, and identified the potentially oncogenic gene MRPL21." (PMID 40713706, 2025). "CCK8, EdU, and colony formation assays demonstrated that PARP1 overexpression significantly reversed the inhibitory effects of MRPL21 knockdown on tumor cell proliferation." (PMID 40713706, 2025). "Conversely, high expression of MRPL21 in tumor cells promoted mitochondrial function." (PMID 40713706, 2025). "Additionally, wound healing and Transwell assays indicated that PARP1 knockdown reversed the MRPL21-mediated enhancement of tumor cell migration and invasion." (PMID 40713706, 2025). "MRPL21-targeted nanoparticles also achieved effective inhibition of tumor growth in animal models." (PMID 40713706, 2025). "Additionally, MRPL21 influenced DNA repair and cell division through the G2M checkpoint, implicating its dual roles in tumor initiation and progression." (PMID 40713706, 2025). "Subsequently, we validated the expression of MRPL21 in clinical samples, and detected increased transcript and protein levels of MRPL21 in HNSCC tumor tissues." (PMID 40713706, 2025). "In this study, we demonstrated that MRPL21 exhibits significant oncogenic properties in HNSCC, promoting tumor cell proliferation, migration, and invasion." (PMID 40713706, 2025). "MRPL21 affected the mitochondrial OXPHOS process and modulated tumor cell proliferation, metastasis, and autophagy via PARP1 activity and the downstream PI3K/AKT/mTOR signaling pathway, thereby contributing to chemoresistance of HNSCC." (PMID 40713706, 2025). "Mechanistically, MRPL21 upregulated mitochondrial oxidative phosphorylation (OXPHOS) and increased PARylation level, inhibited autophagy through activating the downstream PI3K/AKT/mTOR signaling pathway, and ultimately led to tumor progression and cisplatin resistance in HNSCC." (PMID 40713706, 2025).
tumor (continued). "MRPL21 exhibits tumor-regulatory functions independent of its canonical mitochondrial ribosomal role by interacting with PARP1 in the nucleus, thereby modulating tumor proliferation, migration and EMT processes, as well as cellular sensitivity to chemotherapeutic agents such as cisplatin." (PMID 40713706, 2025).
cancer (3 papers, 2010 to 2025). A tumor composed of atypical neoplastic, often pleomorphic cells that invade other tissues. "Given the critical role of mitochondrial metabolism in cancer, we explored the expression of the MRPL21 gene in different tissue types and various cell subpopulations." (PMID 40713706, 2025). "MRPL21 exhibited high expression levels across multiple cancer types, including HNSCC." (PMID 40713706, 2025). "MRPL21 is highly expressed in several cancers and could be used as a biomarker for cancer prediction." (PMID 34586744, 2021).
head and neck tumors (1 paper, 2025). "Validation using online databases and confirmation in HSCC tissues collected by our research group demonstrated that MRPL21 was highly expressed in head and neck tumors and was significantly associated with poor patient prognosis and reduced survival." (PMID 40713706, 2025). "Collectively, this study provides new insights into the mechanisms of proliferation and metastasis in head and neck tumors, and highlights MRPL21 as a promising therapeutic target for HNSCC, as well as a potential research direction to enhance chemosensitivity." (PMID 40713706, 2025). "In this study, we found that MRPL21 interacted with NDUFS1 and promoted mitochondrial OXPHOS function and NAD + level enhancing energy production and proliferation in head and neck tumors." (PMID 40713706, 2025).
MRPL21 also shares sentences with these, for which no sentence is quoted: head and neck squamous cell carcinoma (2 papers); laryngeal carcinoma (2); breast carcinoma (1); cataract (1); colon cancer (1); esophageal squamous cell carcinoma (1); hypopharyngeal carcinoma (1); lung carcinoma (1); non-small cell lung carcinoma (1).